NANOG (Nanog homeobox)
Diseases named in the same sentence as NANOG in open-access papers (continued):
Sharing a sentence is not in itself a finding about the gene and the disease.
tumor (continued). "p-AKT enhances the expression of the main stemness-regulating transcription factors (NANOG, OCT-4, and SOX2), anti-apoptotic proteins, and HIF1A-mediated hypoxia, promoting self-renewal, tumor progression, chemoresistance and radioresistance." (PMID 38720782, 2024). "In addition, a tumor-burden mice model by cell transplantation further demonstrated the promotion of tumor growth by pMX-CCAT2 in vivo, which was associated with increased levels of cell proliferation factors (Ki67 and CCND1) and cell stemness genes (h-TERT, NANOG, SOX2, KLF4 and OCT4)." (PMID 36672487, 2023). "Hypoxia promotes a stem-like phenotype in tumor cells through the activation of genes such as OCT4, SOX2, c-MYC, CD44, CD133, WNT, Notch, and NANOG, leading to dedifferentiated and undifferentiated tumor phenotypes associated with more aggressive biology." (PMID 38132455, 2023). "Shikonin (SHK), for example, induced apoptosis and inhibited migration, invasion, and xenograft tumor growth, as well as the expression of CSC-related markers (ALDH1, OCT4, SOX2, and NANOG) in OC." (PMID 37445860, 2023). "There is some evidence that under hypoxic conditions, the transcription factor NANOG directly activates the expression of BNIP3L and contributes to autophagy in tumor cells with stem-like and immune-refractory properties which makes them resistant to CTLs." (PMID 38071322, 2023). "Stem cell markers, such as NANOG, OCT3/4 and GDF3, contribute to the maintenance of tumor cell pluripotency, and genes involved in proliferation and cell cycle control, including KI67 and CDK4, promote tumor growth." (PMID 37174085, 2023). "With an increase in tumor weight, we evaluated the stemness markers NANOG, OCT4, and the SIRT1–SOX2 axis in the tumor." (PMID 36830834, 2023). "We confirmed that tumor stemness markers including SOX2, OCT4 and NANOG can be significantly upregulated by treatment of CM from H-TDE-stimulated MRC5 cells." (PMID 37781522, 2023). "Notch, Wnt/β-catenin, and sonic hedgehog signaling pathways are known to play a decisive role in tumor stemness via regulating SOX2 and NANOG expression." (PMID 36396820, 2023). "Adding back NANOG abrogated the tumor growth suppressed by TRRAP silencing, suggesting the pivotal role of NANOG in TRRAP-mediated tumorigenesis." (PMID 37047234, 2023). "SOX-2 labelling was present predominantly in the nucleus, while NANOG and OCT4 were found in the cell nucleus and diffusely in the cytoplasm of tumour parenchymal cells." (PMID 36655039, 2023). "The phenotypes of cisplatin-resistant tumor cells are dependent upon TRPV1, which is a direct transcriptional target of NANOG." (PMID 37165076, 2023). "By contrast, when tumor cells were transplanted with stiff hydrogels into immunocompromised mice, TAZ and NANOG signal form nuclear puncta." (PMID 36646707, 2023). "For instance, CD24-expressing HCC CSCs were found to elevate NANOG expression via the induction of STAT3 phosphorylation, leading to enhanced self-renewal and tumor growth." (PMID 37298124, 2023). "miR-135 is a tumor suppressor, which can target and negatively regulate ZNF217, thereby promoting the m6A modification of NANOG and reducing its expression." (PMID 37901333, 2023). "Pharmacologic inhibition of Wnt signaling pathway by MSAB (10 μM) significantly suppressed tumor sphere formation in SW620 cells and the expression of stemness-related factors NANOG and OCT4." (PMID 37986103, 2023). "This hinted that the knockdown of the major NANOG target gene YAP1 had the most potent effect on HBX and NANOG-mediated anti-tumor effect." (PMID 37744383, 2023). "TRRAP overexpression also increased the mRNA levels of NANOG, while TRRAP knockdown reduced tumor growth in a murine ovarian cancer xenograft model." (PMID 37047234, 2023). "Both fludarabine and ruxolitinib treatments exhibit significant impact on the tumour growth of 22Rv1 line, and diminish the protein level of STAT1, BMI1, SOX2 and NANOG in 22Rv1 tumours when compared with vehicle control." (PMID 35908276, 2022).
tumor (continued). "NANOG suppressed mitochondrial oxidative phosphorylation genes (OXPHOS) and enhanced fatty acid oxidation (FAO) in tumor-initiating stem-like cells." (PMID 36497144, 2022). "Hybrids increase the expression of the stemness factors OCT4, NANOG, SOX2, and LIN28, upregulate CD44 and CD133 as well as promote gastric xenograft tumor growth in vivo." (PMID 35205716, 2022). "The immunohistochemistry results demonstrated that the positive expression of Ki67, NANOG, OCT4, and SOX2 was increased in the tumor tissues of mice following ALKBH5 overexpression, the effect of which was reversed by the silencing of UBE2C." (PMID 36551544, 2022). "In our results, CSCs highly expressed tumor stemness marker genes, SOX2 and NANOG, ZNF and ZBTB families." (PMID 36451812, 2022). "NANOG, OCT4 and SOX2 were over-expressed both in tumor tissues and in cellular spheres built from OCSCs cells circulating inside ascites." (PMID 36612107, 2022). "In the present study, we found that AGK enhanced the tumor sphere potential and the expression of stemness genes increased, such as ALDH1, SOX2, OCT4, NANOG, LIN28 and EOC stemness gene CD44." (PMID 35934718, 2022). "Tissue microarrays of tumor samples for patients between 2007 and 2016 were used for immunodetection of Nestin, SOX2, SOX9, KLF4, NANOG, CD133 cMYC, and Ki67." (PMID 35795469, 2022). "The NANOG/HDAC1 axis controls T cell trafficking and resistance to CTL-mediated killing in multiple types of NANOGhi tumor cells." (PMID 35104240, 2022). "The positive expression of Ki67 and NANOG, OCT4, and SOX2 proteins was found to be decreased in the tumor tissues of mice treated with Exos-sh-NC, which was further reduced in the presence of Exos-sh-ALKBH5." (PMID 36551544, 2022). "NANOG, OCT4 and SOX2 were over-expressed not only in tumor tissues but also in both ascites and spheres built from OCSCs cells." (PMID 35269636, 2022). "Tumor tissue were collected, and OCT4, SOX2, and NANOG expressions were assessed by immunohistochemistry (IHC) staining to investigate the association of stemness markers with overall survival (OS)." (PMID 36085021, 2022). "SOX2, KLF4, NANOG, and OCT4 are notorious for their specific expression in CSCs of HNSCC, which promoted stemness and tumor progression and lead to poor prognosis." (PMID 36451812, 2022). "Thus, our data indicate that anti–PD-1–mediated immune selection depletes tumor cells lacking NANOG while enriching tumor cells that express NANOG, suggesting that NANOG expression in tumor cells could confer a survival advantage under the immune selection pressure imposed by anti–PD-1 therapy." (PMID 35104240, 2022). "Only IL-8 was crucial for self-renewal, tumorsphere formation and tumor initiation capabilities as well as the expression of the stemness markers OCT4, SOX2, and NANOG." (PMID 36118530, 2022). "In this process, NANOG upregulated the membrane-bound complement regulatory protein (mCRP) CD59 through promoter occupancy, thereby contributing to the resistance of tumor cells against complement-dependent cytotoxicity (CDC)." (PMID 35606403, 2022). "IF staining demonstrated co-expression of OCT4 (green) with NANOG (red), SOX2 (red) and KLF4 (red) by cells within the tumor glands (arrowheads)." (PMID 34685477, 2021). "c-MYC (green) was also co-expressed with NANOG (red), SOX2 (red) and KLF4 (red) by cells within the tumor glands (arrowheads)." (PMID 34685477, 2021). "Thereafter, the tumor spheres’ number, ALDH+ cell proportion, stemness genes (SOX2, OCT4, and NANOG), expression, and migratory cells were all reduced in MDA-MB-231-shLDHA cells." (PMID 34178639, 2021). "The results showed that miR-3065-3p overexpression in HCT116 cells led to an increase in the expression of the stem cell markers NANOG, OCT4 and SOX2 in tumor tissue." (PMID 34656128, 2021).
tumor (continued). "Immunofluorescence staining performed on three of the tissue samples showed co-expression of OCT4 and c-MYC with NANOG, SOX2 and KLF4 by tumor gland cells, and expression of OCT4 and c-MYC exclusively by cells within the stroma." (PMID 34685477, 2021). "This cell subset showed increased expression of OCT4, NANOG, and SOX2 and tumor-sphere formation ability." (PMID 34778245, 2021). "The expression of NANOG and OCT4 was evaluated by immunohistochemistry in 122 cases, SOX2 in 121 cases, Nestin in 93 cases and PDPN in 85 cases in which representative tumor tissue was available." (PMID 34201050, 2021). "The stem-cell homeobox transcription factor NANOG is upregulated in alcohol and obesity-HCV-induced mouse models of HCC and in human tumor-initiating cells." (PMID 33747521, 2021). "Myeloid-derived suppressor cells (MDSCs) were one kind of immune cells leading to tumor immune escape, which was verified with cell colony formation, tumor sphere formation, and CSC biomarkers (NANOG and c-MYC)." (PMID 34745015, 2021). "We have previously identified two CSC subpopulations within mHNcSCC: an OCT4+/SOX2+/NANOG+/KLF4+/c-MYC+ subpopulation within the tumor nests (TNs) and an OCT4+/SOX2+/NANOG-/KLF4+/c-MYC+ subpopulation within the peritumoral stroma (PTS)." (PMID 34621666, 2021). "Perinecrotic niches are enriched for cells expressing molecular markers of both hypoxia and GSCs (e.g. SOX2, NANOG, CD133) 24, 25, suggesting a connection between the tumor microenvironment and differentiation state of cells." (PMID 33391498, 2021). "Conversely, our results show that NANOG is a transcriptional activator of CXCR4 expression, suggesting a role for NANOG in tumor progression." (PMID 34638956, 2021). "Further, the gene expression profiling of the tumour exhibited a higher level of EPCAM, CK20, KRAS, AKT1, BRAF and CD133 expression, while lower levels of expression were observed in NANOG, MMP9 and APC genes." (PMID 33092235, 2020). "Striking differences were uncovered regarding the clinical impact of NANOG and SOX2 expression on patient outcome, with distinct prognostic relevance depending on tumor site and lymph node infiltration." (PMID 32635524, 2020). "Several studies reported that CD133 combined with OCT4 and NANOG expression indicate a poor survival prognosis in OSCC patients, suggesting that these CSC markers are predictive indicators of tumour invasiveness." (PMID 32483269, 2020). "On the other hand, in LK0902 and LK0917 tumor cells from tumor cell/CAF spheroids, a tendency to an increase in mRNA expression of NANOG and SOX2 was observed." (PMID 33353547, 2020). "To assess whether the CXCR4 positive cells have the features of the tumor-initiating cells, we compared the mRNA expression levels of stemness-associated markers such as NANOG, OCT4, LIN28, and SOX9 between CXCR4 positive and negative cells by quantitative real-time PCR." (PMID 32232002, 2020). "In BCC, D2 and NANOG co-localize at the very early stages of tumorigenesis, whereas in SCC they co-localize in the late stages of tumor progression." (PMID 32197405, 2020). "We were therefore able to analyze the expression of NANOG, SOX2, OCT4, AGR2, KLF4, and NOTCH1 in only 11 tumor samples and corresponding TANT (22 FFPE tissue samples)." (PMID 32733958, 2020). "We also found important differences in the prognostic significance of NANOG and SOX2 expression, depending on the tumor site." (PMID 32635524, 2020). "Expression of NANOG was in positive correlation with the expression of OCT4 in TANT and tumor samples (rs = 0.846, p = 0.001; rs = 0.713, p = 0.009, respectively)." (PMID 32733958, 2020). "As sphere formation reflects the self-renewal capacity of tumor cells, we analyzed stemness marker genes, SOX2, OCT4, NANOG, and c-MYC." (PMID 33276627, 2020). "Focal adhesion kinase (FAK) inhibitors: Regulated by OCT-3/4 and NANOG 163,164, FAK plays an important role in CSC self-renewal and tumor progression." (PMID 32194856, 2020).
tumor (continued). "Expression of specific markers OCT4, NANOG and SOX2 was increased in PT291 organoids and CLOs compared to the 2D primary cell lines, while PT127 PDX tumour had a similar expression profile to the PT127 CLOs compared to its 2D primary cell line." (PMID 32066753, 2020). "In the next step, expression level of stemness relatedgenes (OCT4, SOX2, KLF4, c-MYC and NANOG) and EMTtranscription factors (CDH1, CDH2, SNAIL1, TWIST1,TWIST2 and ZEB1) were evaluated in all tumor samples andmammospheres." (PMID 31376329, 2020). "Taking advantage of the distinct origin of tumor (human) and stromal (murine) cells in our xenografts, we approached the evaluation of stemness genes NANOG, POU5F1 (OCT4), PROM1 (CD133) and SOX2, from the tumor origin." (PMID 32230715, 2020). "Epigenetic mediators contribute to phenotypic plasticity and tumor progression and frequently overlap with genes involved in reprogramming (such as OCT4 and NANOG)." (PMID 32432029, 2020). "Results revealed that the expression of stem cell markers identified as CD44, NANOG, OCT3/4, and CD24 in tumor cells was strongly attenuated by SR59230A treatment." (PMID 32093135, 2020). "Importantly, human D2, NANOG (encoded by the NANOG1 gene), and NANOG-P8 (a transcribed retrogene of the human NANOG homeobox gene) were all highly expressed in the late stages of human tumorigenesis, which is consistent with their expression during mouse tumor progression." (PMID 32197405, 2020). "Given the strong impairment of ATS1-KO cells to form spheres, we evaluated gene expression levels of NANOG and CDH5 in their primary spheres, according to their alteration in our tumor model." (PMID 32230715, 2020). "The results revealed that the protein expression levels of NANOG, OCT4, and SOX2 were significantly higher in tumour spheres than in their parental cells." (PMID 31889900, 2019). "Tumor spheres derived from OSCC cells are CSC-enriched cell population as stemness transcription factors, NANOG, OCT4, KLF4, LIN28, and SOX2 were enriched in tumor spheres." (PMID 31040921, 2019). "In tumours from two of the four patients (H643 and H637), ML-60218 induced DR2 Alu SINEs, including NANOG-Alu-Sx, and this was accompanied by suppression of NANOG mRNA." (PMID 30820548, 2019). "We provide compelling evidence indicating that tumor cells in patient samples express OCT4, SOX2, and NANOG." (PMID 31885625, 2019). "Otherwise, ALKBH5 knockdown inhibits NANOG expression, reduces BCSC population, and impairs tumor formation in vivo." (PMID 31921664, 2019). "We have demonstrated that this primitive population within MG is localized to both the endothelial and pericyte layers of the microvessels within the tumor by its expression of the ESC markers including OCT4 and NANOG." (PMID 31157231, 2019). "In this study, we found that casticin was highly and specifically cytotoxic to the tumour spheres of NPC cells and suppressed the expression of stemness-related proteins SOX2, NANOG, and OCT-4, suggesting that casticin was able to inhibit NPC stem cells." (PMID 31889900, 2019). "As already alluded above, CSCs within the OSCC tumor nests co-express OCT4, SOX2, NANOG, phosphorylated STAT3 (pSTAT3), CD133, CD44, and c-MYC." (PMID 31861233, 2019). "Results showed that ZBTB28 inhibited NANOG, BMI1, OCT4, KLF4, TIP30 and STAT3 mRNA expression in tumor cells." (PMID 31754389, 2019). "BI 853520 treatment, however, did not alter tumor stem cell marker (SOX2, ALDH1, NANOG, c-myc, CD44, Oct4) expressions of human tumor spheroids formed by different MPM cell lines." (PMID 30539198, 2019). "In order to confirm tumor sphere inhibition by nobiletin, we isolated RNA from the spheres and determine the expression of the SOX2, OCT4, and NANOG genes, which are considered stem cell markers." (PMID 29914089, 2018). "Our observations demonstrate that a ternary complex containing Cx26, NANOG, and FAK plays an essential role in TNBC CSC self-renewal and tumor initiation capacities." (PMID 29422613, 2018).
tumor (continued). "The concordance rate between primary tumours and the matched urine samples (analytical sensitivity) was 77.8% (7/9) for CD24, 70.0% (7/10) for CD49f, and 64.3% (9/14) for NANOG." (PMID 30327565, 2018). "To confirm tumor sphere formation, we analyzed the expression levels of SOX2, OCT4, and NANOG, which are considered to be stem cell markers." (PMID 29914089, 2018). "GSCs-enriched spheres expressed higher levels of the pluripotency markers: NANOG, SOX2, and CD133 as compared to the parental/adherent tumor cells." (PMID 30450051, 2018). "Regarding the role of self-renewal factors such as SOX2, NANOG, KLF4, and SALL4 in biology of tumor cells we assessed the probable role of KCTD12 in regulation of such factors in the levels of mRNA expression." (PMID 30157793, 2018). "OCT4 and NANOG significantly influence EMT change and contribute to tumor migration, invasion, and metastasis in vitro and in vivo." (PMID 30082842, 2018). "In several cell lines, CD133+ cells have been found to overexpress ESC markers, including OCT4 and NANOG, and also display CSC characteristics such as tumor sphere formation, tumorigenicity and chemoresistance." (PMID 28626726, 2017). "Immunohistochemical staining for OCT4, SOX2, and NANOG in OCSCC demonstrates that OCT4 and SOX2 are expressed significantly higher in tumor-adjacent tissue compared to both normal tissue and the tumor." (PMID 28626726, 2017). "While Bulun’s group have reported CD34+/CD49+ cells in myometrial SP which also express KLF4, NANOG, SOX2 and OCT-4 as the possible myometrial stem cells and also tumor initiating cells." (PMID 28438190, 2017). "Quantitative gene expression analysis of circulating tumor cells from OSCC patients demonstrated a significant upregulation in gene expression of CD44v6 and NANOG." (PMID 29156833, 2017). "Blocking the downstream activation of proteins induced by hypoxia (like ALKBH5, CAIX, and NANOG) has been shown to inhibit CSC expansion in the tumor site, decreasing the probabilities for tumor relapse after therapy." (PMID 28473858, 2017). "We confirmed higher expression of pluripotency transcription factors (NANOG, POU5F1, SOX2) and CD133 in cells forming tumor spheres." (PMID 27934912, 2016). "The pluripotency factors, such as NANOG, SOX2, OCT4, and LIN28A, suggest a close relationship between tumor formation and the process of reprogramming mature cells to a more primitive type." (PMID 26910839, 2016). "By triple immunofluorescent staining in which NANOG was substituted for SOX2, a similar small subpopulation of tumor cells with a NANOG+ HIF-1α+ RNApII-S2P-/low phenotype was detected in the vicinity of necrotic areas." (PMID 26799577, 2016). "Compared to tumor sections prepared by control A2780 cells, the expression of NICD1, NANOG, OCT4 and SOX2 was significantly increased in those prepared by galectin-3 overexpressing A2780 cells." (PMID 27626163, 2016). "Crucially, evaluating the presence of a subpopulation of tumor-propagating cells in patient biopsies identified by GLI1 and NANOG expression had prognostic significance." (PMID 26189795, 2016). "Regardless, these observations provide a molecular explanation for rapid promotion of tumor cell epithelial mesenchymal transition (EMT), migration and invasion by NANOG." (PMID 27867534, 2016). "We observed that miR-203 overexpression modulated expression of EMT and tumor stemness factors including suppression of ZEB2, N-cadherin, NANOG, c-MYC, and BMI1 as well as induced E-cadherin expression." (PMID 27589832, 2016). "We determined the expression level of NICD1 and stemness factors, such as NANOG, OCT4 and SOX-2 in tumor sections prepared galectin-3 overexpressing A2780 cells." (PMID 27626163, 2016). "GCSs-enriched spheres expressed higher levels of pluripotency markers: NANOG, POU5F1, SOX2 and CD133 as compared to the adherent tumor cells." (PMID 27934912, 2016).